RACK1 (receptor for activated C kinase 1)
Diseases named in the same sentence as RACK1 in open-access papers (continued):
Sharing a sentence is not in itself a finding about the gene and the disease.
esophageal cancer (3 papers, 2018 to 2023). A primary or metastatic malignant neoplasm involving the esophagus. "Up-regulation of RACK1 confers resistance to radiation in esophageal cancer partially through up-regulating BCL2." (PMID 30537994, 2018).
Huntington disease (3 papers, 2021 to 2024). Huntington disease (HD) is a rare neurodegenerative disorder of the central nervous system characterized by unwanted choreatic movements, behavioral and psychiatric disturbances and dementia. "The RACK1 gene can modulate neurodegeneration by promoting ERK degradation in Machado-Joseph disease (MJD) and Huntington’s disease (HD) models and participates in the process of neuronal differentiation by regulating SCN1A expression." (PMID 36161179, 2022). "Loss of the scaffold protein RACK1 alleviated cell death associated with the expression of polyQ tracts alone, as well as in models of Machado-Joseph disease (MJD) and Huntington’s disease (HD), without affecting proteostasis of polyQ proteins." (PMID 33983927, 2021).
lymph node metastasis (3 papers, 2018 to 2021). "Interestingly, the protein level of RACK1 is decreased in 155 GC tissues compared with paired para-carcinoma tissues, and the level of RACK1 is negatively correlated with the depth of invasion, lymph node metastasis, clinical stage of 155 GC patients." (PMID 33323973, 2021). "The expression of RACK1 was associated with age (P < 0.05) but not gender, Dukes stage, TNM stage, lymph node metastasis, or distant metastasis." (PMID 30962803, 2019).
nasopharyngeal carcinoma (3 papers, 2016 to 2024). A carcinoma arising from the nasopharyngeal epithelium. "The receptor for activated C kinase 1 (RACK1) is involved in various cancers, but its roles in nasopharyngeal carcinoma (NPC) have not yet been fully elucidated." (PMID 27170279, 2016).
osteosarcoma (3 papers, 2023 to 2024). A usually aggressive malignant bone-forming mesenchymal neoplasm, predominantly affecting adolescents and young adults. "Among the top DEPs identifying fibroblastic groups from other pathological subtypes are POSTN, TPM4, RTN4, HNRNPK, and RACK1, which were directly associated with osteosarcoma progression and prognosis." (PMID 37681913, 2023). "This study revealed a novel role of the TRIM26/RACK1 axis in osteosarcoma progression and the underlying mechanism." (PMID 37591850, 2023). "However, RACK1 overexpression in osteosarcoma has been associated with increased proliferation, with a mechanism inhibited by the activity of TRIM26, another E3 ligase." (PMID 38534381, 2024). "Mechanistically, our results suggested that TRIM26 inhibited osteosarcoma progression via accelerating the degradation of RACK1, and thus resulted in the inactivation of MEK/ERK signaling and impeded the EMT process." (PMID 37591850, 2023). "Then, we explored the influence of silencing and overexpressing TRIM26 on RACK1 expression in osteosarcoma cells." (PMID 37591850, 2023). "In conclusion, our study indicated that TRIM26 inhibited osteosarcoma progression via promoting proteasomal degradation of RACK1, thereby resulting in inactivation of MEK/ERK signaling, and impeding the EMT process." (PMID 37591850, 2023). "TRIM26 inhibited osteosarcoma progression via promoting the degradation of RACK1, and thus inactivation of the MEK/ERK pathway." (PMID 37591850, 2023). "We further investigated the role of RACK1 in the mechanism by which TRIM26 inhibits the progression of osteosarcoma." (PMID 37591850, 2023). "Thus, further studies are needed to determine if the degradation of HIF1-α by RACK1 would be exploitable for osteosarcoma therapy." (PMID 38534381, 2024). "Moreover, we manipulated the expression of RACK1 in TRIM26-upregulated or TRIM26-silenced osteosarcoma cells through plasmid or siRNA transfection." (PMID 37591850, 2023). "Therefore, we could conclude that TRIM26 inhibits cell proliferation and invasion in osteosarcoma through destabilizing RACK1 and thus inactivation of MEK/ERK signaling." (PMID 37591850, 2023). "However, it is still unclear about the role of RACK1 in osteosarcoma." (PMID 37591850, 2023). "Taken together, these results suggest that overexpression of TRIM26 inhibits tumor growth by destabilizing RACK1 and thus inactivation of MEK/ERK signaling in osteosarcoma." (PMID 37591850, 2023). "We found that overexpression of TRIM26 increased the ubiquitination of RACK1, whereas depletion of TRIM26 significantly decreased RACK1 ubiquitination in osteosarcoma cells." (PMID 37591850, 2023). "RACK1 (receptor for activated C-kinase 1) was dose-dependently decreased by catalpol both in MG63 and U2OS osteosarcoma cells, indicating that catalpol could inhibit osteosarcoma progression via epithelial–mesenchymal transition inhibition." (PMID 37681913, 2023). "Immunoprecipitation assay in 143B cells suggested that RACK1 was precipitated by TRIM26 and reverse immunoprecipitation confirmed that TRIM26 could also be precipitated by RACK1 in osteosarcoma cells." (PMID 37591850, 2023).
adenoma (2 papers, 2004 to 2019). A neoplasm arising from the epithelium. "Immunohistochemical staining was performed to detect the expression of RACK1 in human CRC, adenoma, and normal tissues." (PMID 30962803, 2019). "RACK1, ACBP, CDH17 and EEF1G were significantly overexpressed in low-grade adenomas, whereas DEFA5 was significantly overexpressed in high-grade adenomas and suppressed in adenocarcinomas." (PMID 14710232, 2004). "Moreover, RACK1 was significantly overexpressed in CRC and adenoma tissues compared with its expression in normal tissues (P < 0.05)." (PMID 30962803, 2019).
alcohol addiction (2 papers, 2011 to 2016). "RACK1 in humans has been implicated in myriads of neuropathological diseases including Alzheimer and alcohol addictions." (PMID 26941753, 2016). "Interestingly, the altered compartmentalization of RACK1 in response to alcohol exposure in specific brain regions also contributes to neuroadaptations that underlie the development of alcohol addiction." (PMID 21978545, 2011). "In summary, the altered compartmentalization of RACK1 in the presence of alcohol in specific brain regions results in diverse physiological consequences that both contribute to, and prevent, the development of behaviors associated with alcohol addiction." (PMID 21978545, 2011). "Furthermore, we obtained data to suggest that the functional outcomes of the altered localization of RACK1 in the presence of alcohol are diverse, as RACK1 contributes both to mechanisms that underlie but also those that prevent the escalation of behaviors that underlie alcohol addiction." (PMID 21978545, 2011). "The interest in the potential role of RACK1 in alcohol addiction was initiated with the observation that exposure of several cell lines as well as primary neurons to alcohol results in a dose- and time-dependent translocation of RACK1 to the nucleus." (PMID 21978545, 2011). "Importantly, molecular and behavioral studies suggest that RACK1 and BDNF are part of an endogenous homeostatic pathway that delays or prevents the development of alcohol addiction." (PMID 21978545, 2011).
asthma (2 papers, 2020 to 2022). "Primary human bronchial cells from asthmatic patients and conditioned knockout mice would have provided further insight into the beneficial effect of RACK1 in asthma." (PMID 32064783, 2020). "RACK1 is the downstream target gene of TGF‐β1 shown to enhancement in asthma mice in our previous study." (PMID 32064783, 2020). "Our findings may provide a new insight into understanding the regulation mechanism of RACK1 in asthma pathogenesis." (PMID 32064783, 2020). "In this study, 10 hub targets of RDN were identified for asthma treatment, and RACK1 and SIRT1 were shown to play important roles in asthma." (PMID 35399637, 2022).
cardiac hypertrophy (2 papers, 2013 to 2018). "PKCs are an important trigger of cardiac hypertrophy and activation of PKCε leads to hypertrophy in two ways either by Gαq overexpression or by its association with the receptor for activated C kinase 1 (RACK1), which ultimately leads to cardiac hypertrophy." (PMID 30186311, 2018).
dementia (2 papers, 2017 to 2022). Loss of intellectual abilities interfering with an individual's social and occupational functions. "Significant loss of RACK1 has been associated with dementia." (PMID 28978127, 2017). "Indeed, RACK1 levels have been found to be decreased in post-mortem AD patients’ samples —although discordant data were also reported —suggesting a potential involvement of RACK1 in altered PKC activation associated with dementia." (PMID 36010666, 2022).
Fulminant hepatitis (2 papers, 2022 to 2024). Acute hepatitis complicated by acute liver failure with hepatic encephalopathy occurring less than 8 weeks after the onset of jaundice. "Previous studies have reported implications of MDM2 and COP1 that targeted STAT3 for degradation in tumorigenesis, and involvement of MDM2 in RACK1-abrogated HDAC1 degradation during the pathogenesis of fulminant hepatitis." (PMID 39024388, 2024).
heart failure (2 papers, 2013 to 2019). Inability of the heart to pump blood at an adequate rate to meet tissue metabolic requirements. "11, blocking protein–protein interaction between βIIPKC and its anchor protein (RACK1) with βIIV5-3 (the global inhibitor of βIIPKC15) improved isolated cardiomyocyte and whole heart contractility properties as well as cardiac remodeling in rats with myocardial infarction-induced heart failure." (PMID 30659190, 2019).
immunotoxicity (2 papers, 2021 to 2025). "Since RACK1 plays a pivotal role in immune cell activation, and a complex hormonal balance is involved in the control of its expression, it could represent a useful tool for the screening of EDCs and their immunotoxicity." (PMID 34621174, 2021). "Consistently, this EDC mechanism of immunotoxicity was also found with the xenoestrogenic mycotoxin zearalenone (ZEA) and the synthetic estrogen ethinylestradiol (EE), which were reported to increase RACK1 expression and correlated with significant LPS-induced cytokine release and CD86." (PMID 39846545, 2025).
keloid (2 papers, 2023 to 2024). An irregularly shaped, elevated mark on the skin caused by deposits of excessive amounts of collagen during wound healing. "RACK1 is known to inhibit collagen synthesis in keloid fibroblasts by suppressing the TGF-β1/Smad signaling pathway." (PMID 39606233, 2024). "CircFoxp1 can downregulate RACK1 expression, potentially serving as a modulator of cell proliferation and apoptosis throughout the keloid formation process." (PMID 39606233, 2024). "Thereafter, our RNA pull-down experiment identified that the RNA binding protein RACK1 is a potential target of circFoxp1 and may serve as a regulator of cell proliferation and apoptosis throughout keloid formation." (PMID 37993257, 2023). "As revealed in a previous study, reducing RACK1 could promote keloid formation." (PMID 37993257, 2023).
leishmaniasis (2 papers, 2011 to 2019). Infectious disease that is transmitted through the bite of hematophagous female phlebotomine sand flies. "For example, in cancer metastasis, acute pancreatitis, Cardiovascular disease, plant pathogenic viruses using IRES, and Leishmaniasis, RACK1 expression has been shown to produce poor prognosis." (PMID 31143369, 2019).
leukemia (2 papers, 2019 to 2022). A malignant (clonal) hematologic disorder, involving hematopoietic stem cells and characterized by the presence of primitive or atypical myeloid or lymphoid cells in the bone marrow and the blood. "The Re trajectory (cluster 5 towards cluster 9) is hallmarked by upregulation of numerous genes required for differentiation, leukemia progression and chemo-resistance, including RACK1, EREG and LOXL1." (PMID 35986270, 2022).
liver fibrosis (2 papers, 2013 to 2015). "Though RACK1 has been reported to be implicated in the development of several kinds of diseases, the role of RACK1 in liver fibrosis is little understood." (PMID 23555900, 2013). "Our results suggest RACK1 as a downstream target gene of TGF-β1 involved in the modulation of liver fibrosis progression in vitro and in vivo, and propose a strategy to target RACK1 for liver fibrosis treatment." (PMID 23555900, 2013). "We next evaluated the expression of RACK1 in liver biopsy samples from patients with liver fibrosis." (PMID 23555900, 2013). "RACK1, the receptor for activated C-kinase 1, is a classical scaffold protein implicated in numerous signaling pathways and cellular processes; however, the role of RACK1 in liver fibrosis is little defined." (PMID 23555900, 2013). "In our study, we also identified RACK1 as a novel downstream target of TGF-β1 in liver fibrosis through activating NF-κB." (PMID 23555900, 2013). "RACK1 expression in α-SMA+ cells positively correlated with the stage of liver fibrosis (F = 9.05, p<0.001)." (PMID 23555900, 2013). "Our data suggest RACK1 as a novel biomarker in the initiation and progression of liver fibrosis, and propose a strategy to target RACK1 as a potential adjuvant therapy for liver fibrosis treatment." (PMID 23555900, 2013). "Our results suggest RACK1 as a downstream target gene of TGF-β1 involved in the modulation of liver fibrogenesis, and propose a strategy to target RACK1 for liver fibrosis treatment." (PMID 23555900, 2013). "The expression of RACK1 in fibrous septum is up-regulated, with the stage of liver fibrosis increases from F1 to F4." (PMID 23555900, 2013). "A previous research implied that RACK1 associated with ADAM12 and promoted its translocation to membrane in PKC-dependent manner in HSCs, suggesting that RACK1 might contribute to the development of liver fibrosis." (PMID 23555900, 2013). "Taken together, these results suggest that RACK1 may contribute to the progression of liver fibrosis in clinical cases." (PMID 23555900, 2013). "Depletion of RACK1 suppresses the progression of TAA-induced liver fibrosis in vivo." (PMID 23555900, 2013). "In addition, the expression of RACK1 in fibrogenic cells also positively correlates well with the stage of liver fibrosis in clinical cases." (PMID 23555900, 2013). "We next determined the role of RACK1 in TAA-induced liver fibrosis in vivo." (PMID 23555900, 2013). "In this study, we demonstrate that the expression of RACK1 is increased in activated HSC in TGF-β1 -dependent manner, and RACK1 promotes the initiation and progression of liver fibrosis by enhancing TGF-β1 and PDGF-induced differentiation, migration and proliferation of HSCs." (PMID 23555900, 2013). "However, the role of RACK1 in liver fibrosis is little defined." (PMID 23555900, 2013). "Our previous report suggests that the scaffold protein RACK1 is up-regulated in activated HSCs through TGF-β1/NF-κB signaling and plays a critical role in modulating the progression of liver fibrosis." (PMID 25822822, 2015). "To understand the role of RACK1 in the development of liver fibrosis, we examined the expression pattern of RACK1 in HSCs using the mouse model of TAA-induced liver fibrosis." (PMID 23555900, 2013). "Since RACK1 has been reported to be involved in the regulation of cellular apoptosis and ADAM12 translation, it is likely that the up-regulation of RACK1 induced by TGF-β1 may contribute to liver fibrosis on other aspects." (PMID 23555900, 2013).
myocardial infarction (2 papers, 2019 to 2025). Gross necrosis of the myocardium, as a result of interruption of the blood supply to the area, as in coronary thrombosis. "Regarding the named genes of this subgroup, some previous studies have shown that RACK1 interacted with some protein to form RACK1 protein complexes and participated in the process of fibrosis after myocardial infarction." (PMID 40454289, 2025).
Pasteurella multocida infection (2 papers, 2023 to 2025). "Receptor for activated C kinase 1 (RACK1), a scaffold protein, regulates NF-κB and promotes NLRP3 inflammasome activation during Pasteurella multocida infection." (PMID 40307577, 2025).
retinal degeneration (2 papers, 2021 to 2023). Degeneration of the retina. "Together, these results demonstrate that knocking down of RACK1 significantly alleviated retinal degeneration and delayed motor neuron dysfunction caused by expression of hTDP-43WT or hTDP-43Q331K in D. melanogaster." (PMID 38111057, 2023).
schizophrenia (2 papers, 2023). A major psychotic disorder characterized by abnormalities in the perception or expression of reality. "We thus characterized organellar NHE expression, co-immunoprecipitation with RACK1, and Triton X-114 (TX-114) phase partitioning in dorsolateral prefrontal cortex of 25 schizophrenia and 25 comparison subjects by Western blot analysis." (PMID 36732328, 2023).
thymoma (2 papers, 2009 to 2016). A neoplasm arising from the epithelial cells of the thymus. "It was firstly described that Rack1 overexpression could produce resistance to dexamethasone and ultraviolet-induced apoptosis in mouse thymoma-derived cell line W7.220." (PMID 27644318, 2016).
ulcerative colitis (2 papers, 2025). An inflammatory bowel disease involving the mucosal surface of the large intestine and rectum. "RACK1 was significantly decreased in IBD, especially in ulcerative colitis." (PMID 39693354, 2025).
acute kidney injury (1 paper, 2015). Sudden and sustained deterioration of the kidney function characterized by decreased glomerular filtration rate, increased serum creatinine or oliguria. "Selective deletion of RACK1 in the kidneys, and possibly to the renal tubular system, will be necessary to eventually define the importance of RACK1 in the kidney during acute kidney injury." (PMID 26300785, 2015).
acute myeloid leukemia (1 paper, 2016). Acute myeloid leukemia (AML) is a group of neoplasms arising from precursor cells committed to the myeloid cell-line differentiation. "In consistent, it was reported that Rack1 promoted proliferation of acute myeloid leukemia (AML)-derived cell line THP-19." (PMID 27644318, 2016).
Ataxia (1 paper, 2024). Ataxia refers to impaired coordination of voluntary muscle movement. "A specific knockout of Rack1 in mid‐embryonic neural stem cells using hGFAP‐Cre leads to severe brain and cerebellum developmental defects in mutant mice, resulting in ataxia and balance deficits." (PMID 38523594, 2024).
atherosclerosis (1 paper, 2024). A disease characterized by the build-up of fatty material and calcium deposition in the arterial wall resulting in partial or complete occlusion of the arterial lumen. "In addition, a study on autophagy showed that FGF21 upregulation of RACK1 induced autophagy and inhibited atherosclerosis." (PMID 38451046, 2024).
Atrophy (1 paper, 2008). Any weakening or degeneration, especially through lack of use. "In this perspective, we think that our approach has given a good contribution: in fact we were able to identify some proteins and transcription factors, such as SMAD3/4, GNB2L1/RACK1, MYC, MAX and JUN whose functions have been studied extensively in tumours and in some atrophy models." (PMID 19108710, 2008).
autism (1 paper, 2022). Persistent deficits in social interaction and communication and interaction as well as a markedly restricted repertoire of activity and interest as well as repetitive patterns of behavior. "In conclusion, here we find that ribosomal RACK1 is required for neuronal development and the loss of RACK1 ribosomal function may contribute to neurodevelopment disorders such as autism." (PMID 36233159, 2022).